NGFR (nerve growth factor receptor)
Diseases named in the same sentence as NGFR in open-access papers (continued):
Sharing a sentence is not in itself a finding about the gene and the disease.
melanoma (continued). "To ascertain whether endogenous TAp73 and NGFR associate, we utilized the melanoma cell line SK-MEL-147 and immunoprecipitated NGFR with p73 antibody, confirming endogenous interaction." (PMID 32285119, 2020). "Then, we performed RNA sequencing on three matched parental and TR melanoma cell line pairs and determined whether the NGFR signature was enriched in the TR cells, which was indeed the case." (PMID 32770055, 2020). "Importantly, we confirmed that the melanoma de-differentiation phenotype was usually concordant between the tumor biopsy (defined by NGFR positivity) and the corresponding PD1 PROG cells models." (PMID 32312968, 2020). "Thus, the conclusion that the inverse correlation exists between MITF-positive and NGFR-positive cells cannot be applied for all melanomas developing drug resistance." (PMID 31936151, 2020). "Most recently, a clinical gene profiling study suggested that NGFR might play a divergent role in melanocyte and melanoma development through two different signaling pathways." (PMID 32686661, 2020). "However, it remains largely elusive how NGFR executes its oncogenic role in melanoma development and metastasis." (PMID 32686661, 2020). "Later, NGFR was shown to be critical for melanoma metastasis." (PMID 32686661, 2020). "We therefore analyzed a dataset of untreated melanomas from patients using IHC of NGFR." (PMID 32770055, 2020). "To investigate changes in NGFR levels across a larger cohort of BRAF‐mutant melanoma patients, we analyzed two published RNA‐seq datasets involving matched samples from 21 tumors pre‐treatment and following emergence of resistance to different combinations of RAF/MEK inhibitors." (PMID 28069687, 2017). "Also, we detected the high expression of NGFR in several melanoma cell lines and primary human gliomas." (PMID 27282385, 2016). "Also, NGFR was highly expressed in a number of cancers, including the cancer initiating cells of melanoma, squamous cell carcinomas, osteosarcoma, brain cancer, breast cancer, and neuroblastoma." (PMID 27282385, 2016). "In this respect, the influence of IFN-γ on melanoma-specific regulators of the dynamic plasticity of the cell phenotype, including microphthalmia-associated transcription factor (MITF) and nerve growth factor receptor (NGFR)/CD271 can affect the clinical efficacy of ICIs." (PMID 40108693, 2025). "Previous study indicated that, small EVs (sEVs) derived from metastatic melanoma cell lines were enriched in nerve growth factor receptor (NGFR, p75NTR), could spread through the lymphatic system, and were taken up by lymphatic endothelial cells, supporting lymph node metastasis." (PMID 40093910, 2025). "Next, we asked whether NGFR also protects melanoma cells from NK cell killing in vivo." (PMID 36638181, 2023). "However, analysis of NGFR-regulated gene sets did not reveal any correlation with established invasiveness programs in melanoma cells, raising the question of how NGFR might promote metastasis formation." (PMID 36638181, 2023). "Therefore Ecad+ melanoma cells can turn into NGFR+ cells and vice versa." (PMID 36435874, 2022). "One critical effect of TNFα is the induction of melanoma dedifferentiation, characterized by the downregulation of the melanocytic antigen Melan A (MLANA gene) and the microphthalmia-associated transcription factor MITF, and the upregulation of NGFR and the AXL receptor tyrosine kinase." (PMID 34073253, 2021). "We first determined whether HSP90 inhibition changes NGFR expression in melanoma cell lines." (PMID 32770055, 2020).
melanoma (continued). "In addition to expression of AXL, NGFR and a lineage-specific transcription factor MITF, expression of SOX transcription factors that are associated with control of cancer cell plasticity, is broadly used to classify the phenotypes of melanoma cells." (PMID 31936151, 2020). "All differences in the composition of subpopulations, namely NGFR-positive, MITF-positive and Ki-67-positive cells observed in this study between normoxia and hyperoxia, were cell-line specific but also point at oxygen as the causative factor of melanoma heterogeneity." (PMID 31461993, 2019). "The stress response involves chromatin remodeling and activation of signaling cascades and is characterized by an increase in expression of the nerve growth factor receptor CD271, a proposed marker of melanoma stem cells, and one that may suppress CD8+ T cell function." (PMID 29088901, 2017). "In addition to the xenograft model generated by human lung non-small cell carcinoma H460 cells, NGFR has also been shown by others to enhance cell survival of schwannoma, melanoma, and breast cancer, and to promote metastasis of glioma, melanoma, and head and neck cancers." (PMID 27282385, 2016). "In particular, melanoma-derived small EVs carrying p75NTR/NGFR can induce lymphangiogenesis and create a premetastatic niche in lymph nodes, promoting melanoma metastasis." (PMID 39863771, 2025). "Mesenchymal and neural-crest tumor states (MART1− NGFR+ and/or SOX9+) emerged only in invasive melanomas, including RGP and VGP regions." (PMID 40667360, 2025). "We then mimicked the melanoma cell states identified by the Visium sequencing using mIF antibodies for SOX10, MITF, B2M and NGFR." (PMID 38594286, 2024). "It has been confirmed that melanoma cells can release a series of cytokines, including VEGF-C, nerve growth factor receptor (NGFR), CXCL5, CD147, and Apelin, for lymphatic remodeling and lymphangiogenesis." (PMID 37519819, 2023). "Mechanistically, NGFR leads to down-regulation of NK cell activating ligands and simultaneous up-regulation of the fatty acid stearoyl–coenzyme A desaturase (SCD) in melanoma cells." (PMID 36638181, 2023). "To unravel NGFR-driven properties of MBM, we used a customized shRNA targeting the exon 3 of NGFR to perform a stable, doxycycline (DOX)-inducible knockdown (KD) in conventional melanoma cells (A375, WM35) and BMCs ~7–14 days after DOX-treatment." (PMID 36435874, 2022). "NGFR, and its ligand BDNF, actively mediate this resistance to T cell-induced lysis, as their knock-down sensitized melanoma cells to MART-1 T cells." (PMID 35432344, 2022). "It has been shown that the expression of melanoma stem cell markers including CD44, NGFR, SOX10, SOX2, and SOX4 was increased by IDTCs." (PMID 36224606, 2022). "Directly, a NGFR transcriptomic signature is elevated in persister cells that survive ICI treatment and that among four mouse melanomas that mimic human transcriptomic profiles, de-differentiated cancers were resistant to anti-PD1 therapy." (PMID 36271142, 2022). "As solTNF-mediated upregulation of CD271 (low affinity nerve growth factor receptor; p75NTR) has been reported to mediate resistance to MAPKi by BRAFV600E+ melanomas, we also measured the expression of this receptor by flow cytometry." (PMID 35879777, 2022). "In fact, AXL was induced (fold change > 1.5) in only 4/14 (29%; SCC14-0257, HT144, MelAT, D24M) while NGFR was induced (fold change > 1.5) in 4/14 (29%; NM16, MM200, HT144, D22) dedifferentiated melanoma cell lines." (PMID 34073253, 2021). "We examined TNFα effects on melanoma differentiation by analyzing the accumulation of the key marker proteins MITF, Melan A, AXL and NGFR in the 40 melanoma cell lines." (PMID 34073253, 2021). "Exposure of melanoma cells to BRAF and MEK inhibitors has been shown to slow growth and result in increased expression of NGFR and ECM and focal adhesion genes." (PMID 33438577, 2021).
melanoma (continued). "MNK1/2 inhibitors, which block eIF4E phosphorylation, decreased melanoma cell invasion, restored MITF expression and repressed NGFR expression in BRAFi-resistant cells, and cooperatively inhibited their growth in combination with vemurafenib." (PMID 34604096, 2021). "For instance, subpopulations of melanoma cells expressing high levels of EGFR and NGFR have been identified inside of tumors before therapy; it has been demonstrated that they are responsible for therapeutic relapse." (PMID 34830940, 2021). "The nerve growth factor receptor CD271 regulates the survival and apoptosis of neurons within the CNS and basic properties of melanoma cells like tumorigenicity, plasticity, and self-renewal." (PMID 32878000, 2020). "These melanoma cells express high levels of the neurotrophic factor brain-derived neurotrophic factor (BDNF), and inhibition of either BDNF or NGFR enhances sensitivity to T cell-mediated tumor killing." (PMID 32770055, 2020). "With these in mind, we searched for molecular signs of neoneurogenesis in melanoma by estimating the levels of NGF, NGFR and BDNF, in conjunction with invasive phenotypes." (PMID 33339112, 2020). "Indeed, NGFR has been shown to play a tumor supportive role in a variety of cancers, such as enhancing cancer cell survival in breast cancers, squamous cell carcinomas, melanomas, and schwannoma, and promote an invasive phenotype in gliomas, melanomas, and head and neck carcinomas." (PMID 32285119, 2020). "We identified genes that were specifically upregulated in NGFRhi melanoma PDX compared with NGFRlo ones, and combined them to generate a tumor-intrinsic NGFR signature." (PMID 32770055, 2020). "Nerve growth factor receptor (NGFR, CD271, or p75NTR) is highly expressed in melanoma-initiating cells (MICs) and is critical for their proliferation and tumorigenesis, and yet the underlying mechanism(s) remain incompletely understood." (PMID 32686661, 2020). "In conclusion, we propose that this study merits the development of NGFR-specific therapy, aiming to revert T cell- and ICB-resistance of melanoma." (PMID 32770055, 2020). "We then analyzed NGFR and SOX2 protein levels in both adherent and sphere melanoma cells by western blot (WB) analysis, as both of the proteins have been used as markers for MICs15,27." (PMID 32686661, 2020). "Here we observed high cell surface and total levels of nerve growth factor receptor/CD271, a marker of melanoma-initiating cells, in sub-populations of chemoresistant cell lines." (PMID 28112719, 2017). "In the present study, the effect of ethanol exposure on the expression of the nerve growth factor receptor, CD271, in human FEMX-I melanoma cells was investigated." (PMID 26622576, 2015). "Here we confirmed that the nerve growth factor receptor (CD271) is a crucial determinant of tumorigenicity, stem-like properties, heterogeneity and plasticity in melanoma cells." (PMID 24799129, 2014). "Although this and additional factors (like JARID1B, NES, NGFR/CD271, SOX10, TDGF1/CRIPTO) have been proposed to mark melanoma CSC (reviewed in 13), the existence of CSC in melanoma tumors remains contentious." (PMID 24098529, 2013). "Further, we show that immune-resistant melanomas acquire an invasive, ameboid phenotype characterized by elevated NGFR, PD-L1, and activation of non-muscle myosin light chain 2 (NM II; MLC2)." (PMID 42192125, 2026). "Moreover, CTL therapy can induce melanoma cell dedifferentiation, marked by increased CD271 (NGFR [Nerve growth factor receptor]) expression and reduced MAA levels, including gp100 and MART-1." (PMID 40399946, 2025).
melanoma (continued). "Interestingly, four genes known to be related to cancer cell stemness in malignant melanoma (ALDH1A3, BSG, NGFR, SOX2) were expressed at significantly high levels in CTCs with a high “platelet signature” (p = 0.0204, 0.0012, 0.0183, 0.0200, respectively)." (PMID 40003901, 2025). "Similarly, nerve growth factor receptor (NGFR) induces brain-derived neurotrophic factor (BDNF), which allows melanoma cells to evade T cell killing mechanisms, supporting tumor progression." (PMID 40872475, 2025). "In response to MAPK pathway inhibition, some melanoma cells undergo transcriptional reprogramming towards a melanocytic lineage dedifferentiation cell state characterized by the expression of receptor tyrosine kinases such as AXL, PDGFRβ or NGFR." (PMID 36774337, 2023). "The authors suggest that NGFR is a promising therapeutic target in melanoma and genetically engineered chimeric antigen receptor (CAR)-NGFR NK cells might be used against melanoma." (PMID 37175614, 2023). "In the present study, NGFR was identified in WM115 exosomes, supporting the hypothesis that primary melanoma tumors may release NGFR-containing exosomes to enhance formation of lymph-node metastasis." (PMID 36831440, 2023). "To ensure that this immunosuppressive phenotype was not an artifact of the genetic engineering of NGFR-inducible cells but due to NGFR itself, we further carried out experiments with human melanoma cells endogenously expressing high levels of NGFR." (PMID 36638181, 2023). "We observed that a transcriptional reporter that contained a 1-kilobase fragment of the human NGFR promoter was activated only in a minor subset (0.72 ± 0.49%, range 0.3–1.5), and ~2–4% of A375 melanoma cells revealed stable NGFR mRNA." (PMID 35163127, 2022). "Mean expression values of NGFR- but not Ecad-signature genes significantly (p = 6.2e−03) separated pre- and post-treatment melanoma." (PMID 36435874, 2022). "Interestingly, BRAFi/MEKi treatment increases the level of NGFR (CD271) in drug-adapted, slowly-growing melanoma cell populations." (PMID 36613518, 2022). "NGFR, another melanoma drug-resistance marker whose expression marks neural crest stem cells, was induced upon drug treatment, although at the protein level, NGFR levels were in fact lower in escapees relative to non-escapees." (PMID 33741929, 2021). "Consequently, at the acquired resistance and relapse stage, melanomas show a predominant expression of AXL and NGFR, along with an overall trend towards an AXL/AP-1/TEAD-driven gene signature." (PMID 34604096, 2021). "The majority of melanoma cell lines (23/40: 15/31 cutaneous, 8/9 uveal) showed features of the melanocytic state, including the high expression of MITF and Melan A along with low levels of AXL and/or NGFR." (PMID 34073253, 2021). "In melanoma, MAPK inhibition has been shown to be less effective against cells with high expression of stem-like markers such as nerve growth factor receptor (NGFR, also known as CD271), JARID1B or AXL." (PMID 33800547, 2021). "Another 14/40 melanoma cell lines (13/31 cutaneous and 1/9 uveal) displayed the neural crest-like dedifferentiated subtype with low MITF and Melan A, and elevated, albeit variable levels, of AXL and/or NGFR." (PMID 34073253, 2021). "While we showed that the MNK1/2-eIF4E axis promotes the translation of NGFR, melanoma phenotype switching and therapy resistance, little evidence links NGFR inhibition with a fully reversed switch in melanoma cells." (PMID 34604096, 2021). "Interestingly, NGFR has been shown to play a role in MIC renewal and proliferation, as well as melanoma tumorigenesis and metastasis." (PMID 32686661, 2020). "Consistent with this, we observed that in parental (largely NGFRlo) melanoma cells, NGFR was induced by T cells (independent of their TCR specificity), to return to baseline levels 3–14 days later." (PMID 32770055, 2020).
melanoma (continued). "Two clinical pilot studies investigating whether T cells genetically engineered to express NGFR/CD271 improve the recognition and eradication of melanoma cells in patients with stage III–IV melanoma, started in 2012 and 2013 (NCT01955460, NCT01740557)." (PMID 32878000, 2020). "We also examined the potential influence of melanoma driver oncogenes on IFNγ signaling activity and found that uveal melanoma (UVM) cells show evidence of diminished IFNγ pathway activity with minimal baseline and IFNγ induction of HLA-DR, NGFR, and PD-L2." (PMID 29977240, 2018). "Overall, exposure of melanoma cells to IFNγ induced heterogeneous levels of all target molecules, and induction did not appear to depend on genotype in cutaneous melanomas for PD-L1, PD-L2, HLA-ABC, and NGFR." (PMID 29977240, 2018). "Gene set enrichment analysis (GSEA) showed that similar molecules and pathways accompany increased NGFR expression in 25 BRAFV600E melanoma cell lines found in the Cancer Cell Line Encyclopedia (CCLE) and 128 BRAFV600E melanoma biopsies in The Cancer Genome Atlas (TCGA)." (PMID 28069687, 2017). "Particularly, patient derived NGFR-positive, but not NGFR-negative, melanoma cells were remarkably capable of generating tumors, promoting metastasis, and maintaining self-renewal." (PMID 27282385, 2016). "Moreover, NGFR and phosphorylated MLC2 are consistently enriched at the invasive fronts of primary tumors, metastases, and in immunotherapy-resistant cell lines from melanoma patients." (PMID 42192125, 2026). "Likewise, while many stress responses in melanoma cells were associated with high NGFR and low MITF expression, other stress and invasiveness-inducing conditions resulted in increased NGFR levels but without affecting MITF expression." (PMID 36638181, 2023). "However, the effect of DNAM-1 signaling blockade on NK cell antitumor lysis was not as strong as that of NGFR overexpression alone, suggesting that additional mechanisms of NK cell attenuation are involved in NGFRhigh melanoma cell signaling." (PMID 36638181, 2023). "However, mRNA expression of HLA-C was unaffected in melanoma cells upon NGFR induction, suggesting no interference with NK cell activity." (PMID 36638181, 2023). "However, RANO diminished the emergence of cells of the NCSC state, the NGFR-expressing melanoma state considered the most refractory not only to targeted, but also to immunotherapy." (PMID 37563469, 2023). "In particular, NGFR-driven expression of stearoyl–coenzyme A desaturase 1 (SCD), which catalyzes a rate-limiting step in the synthesis of unsaturated fatty acids, increased melanoma cell membrane fluidity and hampered the surface expression of NK cell activating ligands such as CD112." (PMID 36638181, 2023). "Hence, regulation of NGFR by YY1-controlled metabolic programs appears to contribute to increased invasiveness and metastasis formation observed upon reduction of YY1 expression levels in melanoma cells." (PMID 35693944, 2022). "As NGFR can trigger signaling in the absence of ligand, act as a homodimer or interact with the large number of different partners, it can be a component of diverse and possibly opposing signaling pathways and contribute to phenotype switching in melanoma." (PMID 31936151, 2020). "Therefore, different expression of both, NGFR and MITF in melanoma cells might be responsible for diverse outcomes at the level of phenotype." (PMID 31936151, 2020).